DEPDC5 (DEP domain containing 5, GATOR1 subcomplex subunit)
Diseases named in the same sentence as DEPDC5 in open-access papers (continued):
Sharing a sentence is not in itself a finding about the gene and the disease.
focal epilepsy (continued). "Among the etiologies of focal epilepsy, mutations of the GATOR1 complex genes—comprising NPRL3, NPRL2, and DEPDC5—are known to result in overactivation of mTORC1." (PMID 40971258, 2025). "Heterozygous pathogenic variants in DEPDC5, NPRL2 and NPRL3 are a major cause of focal epilepsy and are collectively classified as “GATORopathies”, with a prevalence of 0.2–3% for deleterious DEPDC5 variants in large international collaborative studies." (PMID 40426219, 2025). "A clinical and genetic study of 73 patients with focal epilepsy (both familial and sporadic) with GATOR1-related gene mutations revealed 22 DEPDC5 mutations in 26 patients with SHE." (PMID 38966089, 2024). "Our study expands the phenotype and genotype spectrum of DEPDC5 and further emphasizes the important role of DEPDC5 in focal epilepsy." (PMID 38974383, 2024). "Overall, germline variants in the GATOR1 complex genes (DEPDC5, NPRL3, and NPRL2) are present in ~10% of focal epilepsy cases, which can be familial or sporadic, especially in familial focal epilepsy with variable foci (FFEVF)." (PMID 34376795, 2022). "For instance, DEPDC5, a component of the GATOR1 complex and a negative regulator of mTOR, has been identified as a gene associated with focal epilepsy in humans." (PMID 34309811, 2021). "The mTOR genes including DEPDC5, TSC1 and TSC2 have been associated with focal epilepsy, as was the case in our study in which the mTOR genes had the highest yield (13/32), although the yield was relatively low in some previous studies." (PMID 31875159, 2019). "With over 180 unrelated families described to date, genes of the GATOR1-mTORC1 pathway (DEPDC5, NPRL2, and NPRL3) are collectively the most frequently mutated genes in focal epilepsies, among which DEPDC5 is predominantly found (85% of all cases)." (PMID 30093711, 2019). "Further DEPDC5 nonsense variants have been reported in two brothers with SUDEP and in one individual from a large French family with focal epilepsy." (PMID 28775708, 2017). "According to current research, approximately 13% of inherited epilepsy syndromes, including FFEVF, and 5% of nonlesional, sporadically occurring focal epilepsy consist of DEPDC5-related mutations." (PMID 40546503, 2025). "Mutations in DEPDC5 cause a broad spectrum of focal epilepsies, both non-lesional and associated with focal cortical dysplasia (FCD) Type II." (PMID 36067010, 2023). "Several candidate rare genetic variants were found in the exome-based research of patients with non-familial non-acquired focal epilepsy and DEPDC5 was regarded as a potential risk factor for drug resistance." (PMID 36408494, 2022). "Those carriers with lesional focal epilepsy showed characteristic FCDII features on MRI, suggesting that DEPDC5 variants may be linked to FCD." (PMID 35163267, 2022). "Loss-of-function variants in DEPDC5 cause familial epilepsy with variable foci (FEVF) which, in small families, typically presents with a mixture of frontal lobe and/or temporal lobe epilepsies though other focal epilepsies and epileptic spasms are also recognized 24–26." (PMID 38101940, 2024). "DEPDC5 (DEP Domain-Containing Protein 5) encodes an inhibitory component of the mammalian target of rapamycin (mTOR) pathway and is commonly implicated in sporadic and familial focal epilepsies, both non-lesional and in association with focal cortical dysplasia." (PMID 36067010, 2023). "Recent studies have linked mutations in several genes involved in the mTOR signaling pathway - such as TSC1, TSC2, MTOR, DEPDC5, NPRL2, and NPRL3 - to the development of focal epilepsies in affected individuals." (PMID 40546503, 2025). "We hypothesized that DEPDC5 loss leading to sustained hyperactivation of mTORC1 signaling alone without neuronal migration defects would be sufficient to cause neuropathological hallmarks of FCD, seizures, and seizure-induced death in a focal epilepsy mouse model." (PMID 40996830, 2025).
focal epilepsy (continued). "These included DEPDC5, which together with NPRL3 reinforces a haploinsufficiency mechanism for GATOR1-related focal epilepsies." (PMID 36865150, 2024). "Besides, variants in DEPDC5 have been detected in many patients with non-familial focal epilepsies." (PMID 35907814, 2022). "Interestingly, within the same family, carriers of the DEPDC5 variants may show lesional or non-lesional focal epilepsy, and some may even be clinically unaffected." (PMID 35163267, 2022). "Mutations in the GATOR1 complex genes, DEPDC5 and NPRL3, play a major role in the development of lesional and non-lesional focal epilepsy through increased mTORC1 signalling." (PMID 36639812, 2023). "Pathogenic or likely pathogenic variants in the DEPDC5, NPRL2 and NPRL3 genes were identified in 8–11% of individuals within focal epilepsy cohorts, mostly comprised of familial non-lesional cases." (PMID 34632383, 2021). "Our group has recently investigated respiratory alterations during seizures in a cohort of patients with focal epilepsy of unknown etiology (MRI negative), describing five patients with ictal central apnea (ICA) and pathogenic DEPDC5 variants." (PMID 40971258, 2025). "Recently, mutations of the DEPDC5 (DEP domain containing 5, involved in g-protein signalling) gene have been demonstrated in patients with cortical dysplasia and in up to 12% of small families of patients with familial focal epilepsy phenotypes, including ADNFLE without demonstrable lesions." (PMID 28120042, 2017). "Consistent with previous work and current knowledge of focal epilepsy, TMS and MRS here revealed no changes in physiological and biochemical factors of GABAergic transmission in DEPDC5 and NPRL3-related epileptic mTORopathies." (PMID 36639812, 2023).
familial focal epilepsy (16 papers, 2016 to 2025). "Focal cortical dysplasia (FCD) is a major cause of refractory epilepsy and is associated with pathogenic variants in mTOR pathway genes, including DEPDC5, the most common cause of familial focal epilepsy." (PMID 40996830, 2025). "Loss of function DEPDC5 variants are recognized to present as focal familial epilepsy; however, associations with comorbid brain malformations and neurodevelopmental disorders have also been reported." (PMID 40206130, 2025). "Heterozygous mutations in the DEPDC5 gene typically give rise to familial focal epilepsy (# 604364)." (PMID 40642607, 2025). "DEPDC5 (DEP domain containing 5): DEPDC5 mutations have been associated with familial focal epilepsy, often with cortical dysplasia." (PMID 37927689, 2023). "Heterozygous mutation of DEPDC5 is emerging as a relatively frequent cause of familial focal epilepsy." (PMID 28974734, 2017). "DEPDC5-related epilepsy is the most common genetic cause of familial focal epilepsy." (PMID 40996830, 2025). "Besides the described case within this report, two other families with familial focal epilepsy with variable foci linked to 22q12 (the region of DEPDC5) have reported individuals with ASD features." (PMID 29075622, 2017). "Finally, mutations in DEPDC5 have been recently identified in numerous cases of familial focal epilepsy." (PMID 27462445, 2016). "DEPDC5-related epilepsy is characterized by focal seizures and includes conditions such as familial focal epilepsy with variable foci (OMIM #620504) and autosomal dominant sleep-related hypermotor epilepsy." (PMID 39767570, 2024). "DEP domain-containing protein 5 (DEPDC5) encodes a protein within the GATOR1 complex that negatively regulates the mTOR pathway, and its mutation is commonly found in patients with familial focal epilepsy." (PMID 35359577, 2022). "Only recently, new genes for familial focal epilepsy (FFE) have been reported from the GATOR1 pathway (DEPDC5, NPRL2, NPRL3) and these were missing from earlier versions of the gene panel CHE-46, CHE-76, CHE-85)." (PMID 29760947, 2018). "Heterozygous germline variants in DEPDC5 were initially implicated in non-lesional (MRI-negative) familial focal epilepsy including familial focal epilepsy with variable foci, autosomal dominant nocturnal frontal epilepsy, and familial temporal lobe epilepsy." (PMID 35163267, 2022). "About 21.4% of patients with DEPDC5-related familial focal epilepsy are refractory to treatments." (PMID 34239491, 2021). "Importantly, the focal Depdc5-knockout mouse model presented here recapitulates the hypothesized 2-hit mechanism of DEPDC5-related familial focal epilepsy." (PMID 40996830, 2025).
Focal cortical dysplasia (11 papers, 2020 to 2025). A type of malformation of cortical development that primarily affects areas of neocortex. "Recently, germline and somatic mutations causing focal cortical dysplasia (FCD) were identified in patients carried with DEPDC5, and proposing a 2-hit- brain somatic and germline–mutational model." (PMID 36685832, 2022). "Focal cortical dysplasias (FCDs) are localized MCDs, formerly believed to mostly result from a toxic insult to the developing brain, but recently also associated with DEPDC5 mutations and somatic mutations in MTOR, PIK3CA, AKT3, PTEN, TSC1 and TSC2." (PMID 35323703, 2022). "DEP-domain containing 5 gene (Depdc5), encoding a repressor of the mechanistic target of rapamycin complex 1 (mTORC1) signaling pathway, has recently emerged as a major gene mutated in familial focal epilepsies and focal cortical dysplasia." (PMID 35269691, 2022).
hepatocellular carcinoma (8 papers, 2012 to 2025). A malignant tumor that arises from hepatocytes. "Recently, two GWAS variants, MICA rs2596542 and DEPDC5 rs1012068 were identified as being associated with the development of HCV-induced hepatocellular carcinoma (HCC) in Japanese patients." (PMID 30723271, 2019). "Variations at DEPDC5 gene have been recently reported as genetic markers associated with hepatocellular carcinoma (HCC) progression in chronic HCV-infected patients." (PMID 25551790, 2014). "Recently, the MICA rs2596542 and DEPDC5 rs1012068 variants in Japanese individuals as well as the HCP5 rs2244546 and PNPLA3 rs738409 variants in European individuals have been found associated with hepatocellular carcinoma (HCC)." (PMID 28928439, 2017). "For example, CRISPR-Cas9-mediated knockout of DEPDC5 revealed its critical role in regulating oxidative stress responses in hepatocellular carcinoma (HCC) cells." (PMID 40968311, 2025). "We herein established hepatocellular carcinoma (HCC) cells knocked out for DEPDC5 by using the CRISPR/Cas9 system, and elucidated that cell viability of the DEPDC5 knockout (DEPDC5-KO) cells was higher than that of the DEPDC5 wild-type (DEPDC5-WT) under leucine starvation." (PMID 29311600, 2018).
Intellectual disability (6 papers, 2017 to 2025). "Baldassari in 201918 reported 83 patients with “language or speech delay” or “intellectual disability” out of 183 (45%), among which 75 had DEPDC5 mutations (48% of total DEPDC5 variant—155), 4 NPRL2 (40% of NPRL2 variants—10), and 4 NPRL3 (4/18, 22% of NPRL3 variants—18)." (PMID 37491868, 2023). "DEPDC5 mutations are also associated with schizophrenia, non-specific psychiatric disorders and ASD, as well as intellectual disability." (PMID 29075622, 2017).
cortical dysplasia (5 papers, 2017 to 2023). "These iPSC and neuronal lines join a small list of lines generated from patients with a mTORopathy, including TSC and individuals with focal cortical dysplasia linked to DEPDC5 mutations." (PMID 32457579, 2020). "The authors proposed a molecular subregional effect, according to which variants closer to the NPRL2/NPRL3 binding site (where DEPDC5 binds to exert its inhibitory effect on the mTOR pathway) may lead to more severe phenotypes featuring cortical dysplasia." (PMID 36067010, 2023). "In this sense, as evidence is still lacking, more effort should be spent on characterizing DEPDC5-related EAF and understanding the extent of mutation-associated cortical dysplasia." (PMID 35153984, 2021).
colorectal cancer (4 papers, 2024 to 2025). A primary or metastatic malignant neoplasm that affects the colon or rectum. "For example, colon cancer cells with homozygous deletion of DEPDC5 exhibited resistance to 5-fluorouracil, a first-line chemotherapeutic in colorectal cancer, and to MK2206, a pan-AKT inhibitor." (PMID 41469472, 2025). "For colorectal cancer, gentisic acid was reported to inhibit metastasis via blocking GPR81-mediated degradation of DEPDC5, thereby inhibiting mTOR-driven EMT signaling." (PMID 41515404, 2025).
developmental epileptic encephalopathies (4 papers, 2021 to 2025). "Other reported seizure types associated with DEPDC5 mutations include mesial temporal lobe epilepsy, autosomal dominant epilepsy with auditory features, infantile spasms, and developmental and epileptic encephalopathy (OMIM #604364)." (PMID 39767570, 2024). "However, mounting research evidence indicates that DEPDC5 gene mutations can also lead to a broader clinical spectrum, including developmental epileptic encephalopathies and febrile seizures." (PMID 41141423, 2025).
gastrointestinal stromal tumor (4 papers, 2021 to 2025). "Subsequently, biallelic loss of DEPDC5 has been found to be common in gastrointestinal stromal tumors with reduced sensitivity to KIT inhibitors, indicating that such alterations can also act as secondary events related to drug resistance." (PMID 35822448, 2023). "However, DEPDC5 inactivating mutations were detected in glioblastoma, breast cancer, and gastrointestinal stromal tumors." (PMID 41469472, 2025). "DEPDC5, a component of the GATOR1 complex, is frequently mutated in gastrointestinal stromal tumours, leading to constitutively high mTORC1 activity." (PMID 36097071, 2022). "Recently, DEPDC5 inactivation was discovered in gastrointestinal stromal tumors (GIST), one of the most common human sarcomas." (PMID 34685669, 2021).
glioblastoma (4 papers, 2016 to 2025). The most malignant astrocytic tumor (WHO grade IV). "Inactivating mutations in GATOR1 components DEPDC5 and NPRL2 have also been identified in glioblastomas and ovarian cancers, and reduced expression of NPRL2 has been detected in a number of other cancers." (PMID 27462445, 2016).
liver fibrosis (4 papers, 2012 to 2021). "In this regard, little is known about the potential effect of variants in MICA and DEPDC5 on liver fibrosis since both GWAS were done in patients in whom liver biopsy was not available." (PMID 30723271, 2019). "Here we sought to dissect the role of MICA rs2596542 and DEPDC5 rs1012068 to liver fibrosis and to HCV-related HCC." (PMID 30723271, 2019). "Similar to MICA, the preoperative, surgical, and tumor factors, except for liver fibrosis stages, were similar between each DEPDC5 genotype." (PMID 23132957, 2012). "To investigate whether hepatic deletion of Depdc5 aggravates ethanol-induced liver fibrosis, we next investigate the expression of fibrogenic markers." (PMID 34267188, 2021).
Seizure (4 papers, 2020 to 2024). A seizure is an intermittent abnormality of nervous system physiology characterized by a transient occurrence of signs and/or symptoms due to abnormal excessive or synchronous neuronal activity in the brain. "Although mutations in GATOR1 genes are associated with epileptic disorders and brain malformations, heterozygous Depdc5+/− rats and mice did not present spontaneous epileptic seizures, but Depdc5+/− rats have subtle cortical malformations." (PMID 34685669, 2021).
autosomal dominant nocturnal frontal lobe epilepsy (3 papers, 2017 to 2021). A seizure disorder characterized by intermittent dystonia and/or choreoathetoid movements that occur during sleep. "Remarkably, DEPDC5 LOF mutations were also found in 13% of the families with a presentation of autosomal dominant nocturnal frontal lobe epilepsy (ADNFLE)." (PMID 34868250, 2021).
brain malformations (3 papers, 2019 to 2025). "Eight of ten APEs (80%) with TSC1 or TSC2 variants but none of the three APEs with DEPDC5 variants had brain malformations including FCD, HS, or TS." (PMID 31875159, 2019).
chronic hepatitis C (3 papers, 2012 to 2017). "Previous studies showed that IL28B and DEPDC5 genotypes were strongly associated with IFN treatment response and HCC development in chronic hepatitis C patients, respectively." (PMID 28797106, 2017).
epilepsy syndrome (3 papers, 2021 to 2024). A syndrome that has a characteristic cluster of clinical features and/or lectroencephalographic (EEG) findings that reflect underlying epileptic activity. "Patients with DEPDC5 mutations, associated with mTOR pathway dysregulation, may benefit from targeted treatments such as mTOR inhibitors (e.g., everolimus), which have shown promise in related epilepsy syndromes." (PMID 39767570, 2024). "Overall, familial cases in this cohort were more likely to exhibit variants in genes associated with established epilepsy syndromes, such as ASH1L, SLC12A5, and DEPDC5." (PMID 39767570, 2024). "The DEPDC5 (DEP domain containing 5, GATOR1 subcomplex subunit) gene has been associated to all the three epileptic syndromes with onset at variable age, thus comprising SHE, FFEVF and EAF, as well as mesial temporal lobe epilepsy." (PMID 35153984, 2021). "Epilepsy syndrome caused by NPRL2 and NPLR3 variations is similar to DEPDC5." (PMID 34376795, 2022).
generalized epilepsies (3 papers, 2020 to 2023). "In contrast, no DEPDC5 mutation was identified in any of the 91 patients with generalized epilepsies." (PMID 32848577, 2020). "In contrast, no DEPDC5 mutation was identified in the 91 patients with generalized epilepsies." (PMID 32848577, 2020).
autism (2 papers, 2021 to 2025). Persistent deficits in social interaction and communication and interaction as well as a markedly restricted repertoire of activity and interest as well as repetitive patterns of behavior. "Finally, disruptions in KLF7, another identified TF here, have been linked to autism‐like phenotypes in animal models, reinforcing the potential broader impact of DEPDC5‐associated transcriptional changes." (PMID 40704780, 2025).
breast carcinoma (2 papers, 2021 to 2025). "For example, missense mutations in metastatic breast cancers are twice more frequent in Nprl2 (1.55%), than in Nprl3 or Depdc5 (0.78%)." (PMID 34685669, 2021).
channelopathy (2 papers, 2018 to 2026). Channelopathies are a group of diseases caused by the dysfunction of ion channel subunits or their interacting proteins. "Discovery of mutations in DEPDC5, NPRL2, and NPRL3 that encode for GATOR1 (negative modulator of mTORC1) have pioneered the channelopathy-independent approach in understanding the pathological process of NFLE." (PMID 30319421, 2018).
Cirrhosis (2 papers, 2014 to 2019). A chronic disorder of the liver in which liver tissue becomes scarred and is partially replaced by regenerative nodules and fibrotic tissue resulting in loss of liver function. "In order to assess the influence of DEPDC5 polymorphism on the risk of progression to cirrhosis or HCC, the genotype distribution and allele frequency of both DEPDC5 SNPs were studied between chronic HCV-infected patients and cirrhotic patients." (PMID 25551790, 2014). "A recent smaller study conducted in Europeans suggested an association between DEPDC5 rs1012068 but not MICA rs2596542 and risk of cirrhosis in chronic HCV infection." (PMID 30723271, 2019).
Epileptic spasm (2 papers, 2020 to 2024). A sudden flexion, extension, or mixed extension-flexion of predominantly proximal and truncal muscles that is usually more sustained than a myoclonic movement but not as sustained as a tonic seizure. "On the other hand, DEPDC5 mutations have been occasionally identified in cases of epileptic spasms; asymptomatic carriers were also common across the DEPDC5 mutation-related families." (PMID 32848577, 2020).